MET (MET proto-oncogene, receptor tyrosine kinase)
Diseases named in the same sentence as MET in open-access papers (continued):
Sharing a sentence is not in itself a finding about the gene and the disease.
cancer (continued). "FERMT1, MET, and MMP3 overexpressed in PC tissues, while the expressions of CARD9 were not outstanding in both normal and cancer tissues in PC." (PMID 37727377, 2023). "In the European Organization for Research and Treatment of Cancer (EORTC) phase II trial 90,101 “CREATE,” the MET inhibitor crizotinib was evaluated in patients with MET-positive and MET-negative ASPS." (PMID 35628499, 2022). "Stable ILEI shRNA knock-down did not influence proliferation or sensitivity towards c-MET-inhibitor induced proliferation arrest in cancer cells, but impaired both c-MET-independent and -dependent cancer cell invasion." (PMID 33596971, 2021). "Although HGF/c‐MET pathway was deemed as a promising therapeutic target, numerous investigations have proven that inhibition of HGF or c‐Met TKI was not an effective and practical therapeutic strategy in suppressing multiple human cancers." (PMID 33751856, 2021). "Meanwhile, it was found that the markers of cancer stem cells (CSC) CD24 was significantly increased and no MET and HER amplications were detected in PC-9-Br compared to PC-9 parental." (PMID 32264860, 2020). "MET copy number gains were detected in SNU5, SNU620, Hs746T, MKN45, EBC-1, and H1993 cancer cell lines, but not in the SNU638 cancer cell line, whereas the MET gene was not amplified in the normal gastric epithelial cell line, HFE145." (PMID 32549194, 2020). "Both MET and EGFR are successful therapeutic targets in other cancers, yet have not been thoroughly tested in TNBC." (PMID 27655711, 2016). "Gefitinib also reduced the levels of β-catenin in cancer cells, however neither fibroblasts nor inhibitors of HGF/MET signaling had any effect on β-catenin levels in DiFi cells." (PMID 27121052, 2016). "Our hit list contains genes coding kinases with established oncogenic functions such as MET, EGFR, AKT, mTOR, RSK2 as well as genes that do not (yet) have an established role in cancer progression (NEK5, SIK2)." (PMID 27374095, 2016). "However, this association with poor prognosis is not always evident with high c-MET protein expression, highlighting the complexities of the MET amplicon’s involvement in cancer." (PMID 33596971, 2021). "Additionally, TNF-α, although not alone, was capable of upregulating MET (receptor for HGF) expression and promoting the antitumor activity of neutrophils in a variety of cancer types." (PMID 32117288, 2020). "We sought to elucidate the mechanism of AKT activation in CRC cells by examining many pathways that have been reported for regulating AKT in cancer cells [such as EGFR, IGFR, FGFR, and MET], and found that none of these pathways were activated in CRC cells by CM from LPECs (data not shown)." (PMID 28453235, 2017). "In this respect, here we suggest that the reduction of EGFR on cancer cell membrane, could not allow EGFR hetero-dimerization with MET and, therefore, subsequently block MET transactivation." (PMID 28978055, 2017). "The majority of known driver gene amplifications (e.g., EGFR, ERBB2, MET, and MYC) and homozygous deletions (e.g., CDKN2A, PTEN, and RB1) were captured, with 320 RACSs (38%) containing at least one known putative cancer driver gene, in addition to 531 RACSs (62%) without known driver genes." (PMID 27397505, 2016). "Combination EGFR and MET inhibition with WZ4002 (a third-generation EGFR-TKI) and crizotinib demonstrated highly efficacious control in these cancer models, but neither of these drugs alone could induce a suppressive response." (PMID 25780909, 2015). "In the area of lower differentiation status where cancer cells are crowded by the active proliferation and have increased nuclear/cytoplasmic ratio without keratinization, we clearly observed a Brm+, CD44+, MET+, and CAV1+ phenotype in almost all cases." (PMID 25673149, 2015).
cancer (continued). "When ARMS cells were transfected for 48 h with ALK, MET or NC siRNA, apoptosis was respectively: 15.6, 14.1 and 12.0 % for RH4, and 14.8, 13.9 and 10.2 % for RH30 cancer cells, respectively, showing that single targeting of ALK or MET proteins did not produce notable programmed cell death." (PMID 26445453, 2015). "CDK8, MET, PRKCZ, and PTK2 also exhibit negative scores against the majority of the cells, indicating inhibition of these hub genes could arrest cell proliferation required during cancer." (PMID 40500799, 2025). "An analysis of the Cancer Cell Line Encyclopedia database revealed that NB cell lines, including NGP and SH-SY5Y, used in the present study for most of the experiments overexpress MET, and SH-SY5Y contains more copy numbers of MET in comparison to other NB cell lines (Data not included)." (PMID 39458991, 2024). "MET amplification and overexpression correlate with constitutive activation of the Met RTK and downstream signaling pathways in the absence of the Met ligand, HGF, in cancer-derived cell lines, indicating that the induction of constitutive Met signaling underlies this clinical observation." (PMID 35249128, 2022).
adenocarcinoma (78 papers, 2000 to 2025). A common cancer characterized by the presence of malignant glandular cells. "Adenocarcinoma histology (p = 0.003) and PD-L1 expression (p < 0.001) were independently associated with MET overexpression." (PMID 41375002, 2025). "KRAS, BRAF, STK11/KEAP1, MUTYH/RET, and RBM10/MET-associated modules showed the opposite trend, having significantly higher frequencies of adenocarcinoma cases as genomic alterations increased (P ≤ 0.02)." (PMID 39664186, 2024). "Two orally administered selective c-MET inhibitors, capmatinib and tepotinib, were also approved after chemotherapy in adenocarcinoma carrying MET exon 14 skipping mutations of about 3%." (PMID 38605928, 2024). "These and 28 other mutations were detected at a significantly higher prevalence in adenocarcinoma cases including therapy-associated MET exon 14 skipping mutations (3.8% vs 0.8%), EML4-ALK fusions (2% vs 0%), and KIF5B-RET fusions (0.5% vs 0.1%)." (PMID 39664186, 2024). "Despite the presence, the pathological type of MET exon 14 skipping mutation is predominantly the below-par differentiated adenocarcinoma." (PMID 37400762, 2023). "This is significantly higher compared to other types of NSCLC patients, e.g., adenocarcinoma who only present with MET exon 14 skipping mutations in 2.3%." (PMID 37445733, 2023). "MET exon 14 skipping mutations occur in about 3–4% of patients with adenocarcinomas and in about 1–2% of patients with other NSCLC histology (squamous and sarcomatoid lung cancer)." (PMID 34425853, 2021). "Oncogenic mutations in MET include MET exon 14 skipping mutations (3–4% of NSCLC adenocarcinomas), MET gene copy number (GCN) gain or amplification, and MET protein overexpression." (PMID 34238332, 2021). "The 5.3% frequency of exon 14 MET mutations was derived from 150 adenocarcinomas carrying similar mean gene mutation frequencies as those previously reported in France for KRAS (23.3%), EGFR (9.3%), and BRAF (0.3%)." (PMID 28418914, 2017). "We tested 81 patients with SC and 150 with adenocarcinoma for somatic mutations affecting both splice sites and intronic non-coding regions immediately adjacent to exon 14 of the MET gene." (PMID 28418914, 2017). "Based on our study findings, SC patients should be screened for MET exon 14 mutations in the same manner as adenocarcinoma patients." (PMID 28418914, 2017). "This study sought to screen mutations affecting MET exon 14 splice sites in a large SC cohort of Caucasian patients, with a large adenocarcinoma cohort as internal control." (PMID 28418914, 2017). "The pattern of MET mutations found by our team was in the range of those recently published for adenocarcinomas." (PMID 28418914, 2017). "The frequency of MET exon 14 splice site mutations was 4.9% for SC and 5.3% for adenocarcinoma patients." (PMID 28418914, 2017). "There were four SC (4.9%) and eight adenocarcinomas (5.3%) exhibiting MET exon 14 mutations." (PMID 28418914, 2017). "Most histological subtypes with MET exon 14 skipping are adenocarcinomas (10/15, 66.7%), followed by pleomorphic carcinomas (3/15, 20.0%)." (PMID 40104449, 2025). "Multivariate analysis revealed significant correlations of MET overexpression with adenocarcinoma histology (OR: 3.85, 95% CI: 1.58–9.45, p = 0.003), and with high PD-L1 expression (≥50%, OR:12.17, 95% CI: 5.19–31.34, p < 0.001)." (PMID 41375002, 2025). "Biopsy confirmed adenocarcinoma (thyroid transcription factor-1 (TTF-1) +, Programmed Death-Ligand 1 (PD-L1) >80%), and next-generation sequencing revealed a MET exon 14 skipping mutation." (PMID 41573491, 2025).
adenocarcinoma (continued). "Most prevalent actionable mutations in adenocarcinoma include KRAS, EGFR, ALK, RET, ROS1, BRAF, HER2, MET." (PMID 37301854, 2023). "Similar to the UW and SU2C mCRPC cohorts, transcriptome analysis revealed that AR-active adenocarcinoma PDX models had negligible MET and RET transcript expression, whereas 3 of 4 SCNPC PDX models and the NCI-H660 cell line had robust MET and RET expression." (PMID 33471819, 2021). "MET inhibitors are now established TKIs in the treatment of NSCLC patients with exon 14 skipping mutation, which is present in 3–4% of patients with adenocarcinomas and 1–2% of patients with other histologies." (PMID 34425853, 2021). "Several previous studies have identified high frequencies of the MET exon‐14‐skipping mutation (approximately 20%) in both PSC34, 57 and PC of the lung, which is higher than in adenocarcinoma." (PMID 32578376, 2020). "We initially focused on patient 29, who had a pT3N0 diffuse subtype adenocarcinoma arising from the gastroesophageal junction with amplification of MET, FGFR2, and CCND1 (eFigure 4A in the Supplement)." (PMID 32338752, 2020). "MKN45 cells were derived from a poorly-differentiated adenocarcinoma of the stomach of a 62-year-old woman and are known for MET amplification." (PMID 29686309, 2018). "Pellino-1 overexpression was significantly higher in patients with adenocarcinoma harboring EGFR mutation, increased EGFR gene copy numbers and MET expression." (PMID 28009353, 2017). "FGFR1 gene amplification was detected in 5 of 24 (21%) SCC models and c-MET gene amplification in one (14%) adenocarcinoma model." (PMID 25470237, 2015). "A recent study demonstrated that adenocarcinoma tumors had a significant increase in the number of MET gene copies indicating that gene amplification is one possible mechanism underlying c-MET overexpression." (PMID 22363766, 2012). "The most prevalent alterations identified by RNA sequencing included fusions or exon skipping mutations involving therapy-associated genes MET (2.9%), ALK (1.7%), ROS1 (0.9%), and RET (0.7%), all of which were detected at a significantly higher frequency in adenocarcinoma cases." (PMID 39664186, 2024). "With that in view, we examined the correlations between MET gene status as assessed by fluorescence in situ hybridization (FISH) with overall survival (OS) and progression-free survival (PFS) in adenocarcinoma patients with EGFR gene mutations who had received gefitinib therapy." (PMID 25886066, 2015). "Taking into account the results of the present meta-analysis it will be interesting to see whether the potential benefit from onartuzumab is present in all the MET positive patients or restricted to MET positive patients with adenocarcinoma only." (PMID 25232729, 2014). "We suggest that the worse overall survival observed in patients with higher gene copy number might be histotype specific and generates the hypothesis that patients with adenocarcinoma and high MET gene copy numbermight potentially benefit from adjuvant chemotherapy after resection." (PMID 25232729, 2014). "Several biomarker-guided therapies have been approved, targeting genes frequently altered in adenocarcinoma, such as EGFR, BRAF, MET, ALK, ROS1, RET and NTRK." (PMID 39199558, 2024). "In some NSCLC patients, mainly adenocarcinoma, molecular alterations in driver genes, like EGFR, KRAS, HER2, ALK, MET, BRAF, RET,ROS1, and NTRK are recognized." (PMID 37346803, 2023).
adenocarcinoma (continued). "Transcriptome analysis of the University of Washington rapid autopsy and SU2C mCRPC datasets revealed upregulated MET and RET expression in SCNPCs relative to adenocarcinomas." (PMID 33471819, 2021). "Our study first indicated that targeting c-MET therapies improved PFS and DCR in advanced or metastatic NSCLC patients, especially in previous treated Asian patients with adenocarcinoma." (PMID 27786238, 2016). "Several of the identified mGISTIC regions harbored known or putative adenocarcinoma driver candidates, such as EGFR, MDM2, KRAS, MYC, TERT, MET, CCND1, NKX2-1/TITF1, CDK4, ERBB2, ID1, RB1, CDKN2A and PTEN." (PMID 24205279, 2013). "The remaining adenocarcinoma cell line H1734 exhibited a moderate activation of the HER1 pathway and a very low activation of the HER2 and c-MET pathways." (PMID 22091388, 2011). "The other adenocarcinoma cell line H1975 showed only moderate activation of HER2, c-MET, and SHC pathways and a low activation of the IGF-1R pathway." (PMID 22091388, 2011). "To further interrogate the translational potential of MET and RET expression and cabozantinib treatment in SCNPC, we evaluated two adenocarcinoma LuCaP CRPC PDX models (LuCaP 86.2CR and LuCaP 147CR), 4 SCNPC PDX models (LuCaP 49, 93, 145.1 and 173.1) and the SCNPC NCI-H660 cell line." (PMID 33471819, 2021). "Considering the adenocarcinomas without any actionable EGFR or BRAF mutations, the percentage of tumors exhibiting MET exon 14 splice mutations was eight out of 100 patients." (PMID 28418914, 2017). "In the subgroup analysis Asian ethnicity, FISH methodology, adenocarcinoma histology and year of diagnosis earlier than 2004 were indicators of a negative effect of MET gene copy number on survival." (PMID 25232729, 2014). "Other examples of carcinogenic drivers for adenocarcinoma include modifications in protein kinase B (AKT), BRAF, human epidermal growth factor receptor-2 (HER2), phosphatidylinositol-4,5-bisphosphate 3-kinase catalytic subunit alpha (PIK3CA), MET, ROS1, RET, and KRAS." (PMID 35004079, 2022). "In contrast with NSCLC, PD-L1 expression in PSCGCC is related to the presence of adenocarcinoma markers such as TTF-1 and/or Napsin A. Another hope for patients with lung SC is the relatively higher frequency in this subtype of exon 14 skipping of MET (hepatocyte growth factor receptor gene)." (PMID 28671973, 2017). "The proportion of sarcomatoid histological subtypes, such as pleomorphic carcinomas, or the presence or absence of adenocarcinomas in the epithelial component, might also have impacted the MET exon 14 rate." (PMID 28418914, 2017). "High MET gene copy number was identified in 33% of adenocarcinoma NSCLC, however, none responded to MET inhibitor." (PMID 29034207, 2017). "As a summary, our study first indicated that targeting c-MET therapies improved PFS and DCR but not OS and ORR in advanced or metastatic NSCLC patients, especially in previous treated Asian patients with adenocarcinoma." (PMID 27786238, 2016).
infection (38 papers, 2008 to 2026). The state of being infected such as from the introduction of a foreign agent such as serum, vaccine, antigenic substance or organism. "Infection of Mrp8;Metfl/fl c-MET-deficient neutrophils resulted in increased ROS release compared to their wild type counterpart." (PMID 35041723, 2022). "We then measured in vivo the production of ROS in c-MET deficient and control neutrophils at the site of infection." (PMID 35041723, 2022). "However, inhibition of c-MET led to the loss of pro-osteogenic effects in hBMSCs with rAd-HGF infection compared with DMSO-treated and rAd-HGF-infected cells." (PMID 29510550, 2018). "In Leishmania mexicana infection, c-MET expression is activated in neutrophils and favors their recruitment to the site of infection." (PMID 38909206, 2024). "To further quantify the infiltration of immune cells upon c-MET inhibition, we assessed the frequency of recruited cells at the site of infection by flow cytometry." (PMID 35041723, 2022). "Here, we aimed to investigate the role of c-MET activation in neutrophils in the context of parasite infection, more specifically following infection with Leishmania mexicana." (PMID 35041723, 2022). "Following infection with L. mexicana, mice with conditional deletion of c-MET in neutrophils controlled significantly better their lesion development and parasite burden compared to similarly infected wild type mice." (PMID 35041723, 2022). "Ten weeks after the infection, infected ears were collected, processed and c-MET expression in neutrophils, monocytes and dendritic cells was analysed by flow cytometry." (PMID 35041723, 2022). "We then assessed if the level of HGF, the only known ligand for c-MET, was regulated at the site of infection." (PMID 35041723, 2022). "Collectively, our data show that c-MET activation in neutrophils contributes to their recruitment following infection, and that L. mexicana induction of c-MET on neutrophils impacts the local pathology associated with this disease." (PMID 35041723, 2022). "An increase in the frequency of CD4+IFNγ+ T cells was observed at the site of infection both in mice genetically deficient for c-MET in neutrophils and in the lesion of mice treated with the c-MET inhibitor capmatinib." (PMID 35041723, 2022). "We then analysed c-MET expression in vivo at the site of infection, during the chronic phase of L. mexicana disease." (PMID 35041723, 2022). "In line with this, we observed c-MET tyrosine phosphorylation at the site of infection in neutrophils as well as in dermal macrophages." (PMID 35041723, 2022). "Two other novel miRNAs, pol-miR-n008-3p and pol-miR-n370-3p, targeted PLD2 and MET, respectively, which have been reported to contribute to the infection and internalization of Yersinia enterocolitica and Listeria monocytogenes, respectively." (PMID 32549342, 2020). "This confirms that c-MET is indeed phosphorylated in the catalytic domain during trophozoite infection." (PMID 32782246, 2020). "Of particular interest was striking multi-residue hyper-phosphorylation of the tyrosine kinase c-MET at the trophozoite stage, and of the serine/threonine kinase B-Raf during the entire infection process." (PMID 33015142, 2020). "We observed a significant decrease in MET protein expression in GC cells after infection with H. pylori, whereas MET mRNA levels remained unchanged." (PMID 30160350, 2018). "Transfection of all studied cell lines with adenoviruses carrying MET WT and MET D1398G mutant was adjusted to multiplicity of infection 10 to 12 adenoviruses per one cell." (PMID 27584154, 2016). "It has been demonstrated that transfection of hepatoma cells with a dominant-negative form of MET leads to a reduction in Plasmodium infection while transfection with a constitutively active form results in an infection increase." (PMID 18989463, 2008).